HIF1A (hypoxia inducible factor 1 subunit alpha)
Diseases named in the same sentence as HIF1A in open-access papers (continued):
Sharing a sentence is not in itself a finding about the gene and the disease.
tumor (continued). "HIF1α acts as a sensor for hypoxic stress and upregulates angiogenic factors and promotes transcription of several genes, including glucose transporters and glycolytic enzymes such as GLUT1 and HK, for tumor survival." (PMID 23718763, 2013). "Thus, the ablation of both HIF-1α and HIF-2α resulted in reduced tumor volume and progression in different cancer models, suggesting that HIF-1α and HIF-2α regulate overlapping pathways." (PMID 23533994, 2013). "HIF-1α is a critical regulator of many hypoxia responses, including resistance to apoptosis and participates in resistance to VEGF inhibition, including Vegf-depleted tumor cells." (PMID 23651517, 2013). "miR-145 suppresses tumor angiogenesis, growth and invasion by lowering the production of the oncogene VEGF-A and by suppressing the expression of the serine/threonine kinase p70S6K1, which promotes HIF-1α and VEGF activities in colon cancer cells." (PMID 23325049, 2013). "HIF-1α and HIF-2α with their opposing and overlapping functions in tumour cells as well as in inflammatory cells of the tumour microenvironment can crosstalk between these populations and have clear effects on tumour metabolism, inflammation, and progression." (PMID 23526956, 2013). "Here we show that minor differences in the molecular nature of KRAS mutations stimulate distinct intracellular signalling pathways in normoxic conditions with different impact in basal levels of HIF-1α VEGF-A production and generation of a distinct vascular network in tumours." (PMID 23506169, 2013). "In cases of G2 adenocarcinomas, 3% of the tumours manifested no HIF-1α expression, over 37% showed + expression, over 37% of them demonstrated ++ expression and almost 22% +++ expression." (PMID 24153191, 2013). "Patterns of tumor PET imaging were then compared to immunohistochemistry and immunofluorescence for markers of proliferation (Ki-67), DNA damage and repair (γH2AX), hypoxia (HIF-1α), and angiogenesis (VEGF)." (PMID 23690748, 2013). "The mechanism by which HIF-1α induces migration warrants further study; establishing a clear link between HIF-1α and survivin in A549 cells could provide new information on the mechanisms by which HIF-1α promotes tumor growth." (PMID 23732337, 2013). "The Kaplan-Meier survival analysis revealed a significantly worse overall survival (P<0.001) and disease-free survival (P<0.001) for patients with nuclear staining of HIF-1α compared with those whose tumours were negative for HIF-1α staining." (PMID 23599780, 2013). "By contrast, HIF-1α is frequently activated in cancer cells, including under normoxic conditions by oncogene products or impaired activity of tumor suppressor genes." (PMID 24312289, 2013). "Moreover, it has been noticed that an enhanced expression of HIF-1α and HIF-2α in tumour cells was strongly correlated with tumour grade and vascularity of GBM tissue specimens." (PMID 23301832, 2013). "SEPT9_i1/HIF-1α interaction plays an important role in upregulation of HIF-1 transcriptional activity by preventing HIF-1α’s ubiquitination and degradation leading to increased tumor growth and angiogenesis." (PMID 23977378, 2013). "The HIF-1α subunit possesses a unique oxygen-dependent degradation domain (ODD) that controls protein stability and plays a crucial role in regulating the state of oxygen in tumor microenvironment." (PMID 26555969, 2013). "All together, NLGP by inhibiting VEGF, its transcription factor HIF1α and its receptor VEGFR2 potentially restricts the formation of a hypoxic state in the tumor vicinity that may suppress atypical angiogenesis and metastasis." (PMID 23785504, 2013). "Once TAMs are recruited to the hypoxic areas, TAMs respond to hypoxia by upregulating hypoxia-inducible transcription factors (e.g., HIF-1α) for metabolic adaption, leading to an increase in transcription of a number of genes (e.g., VEGF, CXCL8) involved in regulating tumor vascularization." (PMID 24314323, 2013).
tumor (continued). "Although hypoxia-mediated activation of the Notch1 pathway plays an important role in tumor cell survival and invasiveness, the interaction between HIF-1α and Notch1 has not yet been identified in T-ALL." (PMID 23289374, 2013). "CXCR4 is one of the target genes of HIF-1α and it has been well documented that hypoxia-induced expression of CXCR4 in various tumor cells is regulated by the activation of HIF-1α, thereby promoting the aggressiveness of tumor." (PMID 23671625, 2013). "CSCs have been considered to be dependent on HIF-1α and HIF-2α for survival and tumor growth." (PMID 23840432, 2013). "Perinecrotic tumor cells distant from the supplying vessels under hypoxic stress express HIF-1α, whereas nonnecrotic tumor shows diffuse expression throughout the tumor including the tumor cells close to the blood vessels." (PMID 24165149, 2013). "Interestingly, ASCs, which were HIF-1α and aromatase double-positive and which were single-positive for HIF-1α or aromatase, were significantly increased in tumor patients compared to cancer-free women." (PMID 23566437, 2013). "HIF1α is not strongly expressed in normal tissues under normoxic conditions and presents a potential therapeutic target to selectively suppress tumor glucose metabolism." (PMID 24280044, 2013). "Of note, the addition of Dox to HIF-1α knockdown did not add any further effect on tumor growth inhibition and also did not further decrease MVD or increase endothelial cell-specific apoptosis." (PMID 22684860, 2013). "Interestingly, while hypoxia induced both HIF-1α and HIF-2α expression in macrophages, tumor supernatants (TSN) under normoxic condition induced only the expression of HIF-2α." (PMID 24194900, 2013). "In G1 adenocarcinomas almost 28% of the tumours manifested no HIF-1α expression, 61% of them manifested the expression at + level and 11% at ++ level." (PMID 24153191, 2013). "Macrophages respond to hypoxia via HIF1a and upregulate VEGF in hypoxic regions of the tumor." (PMID 23653658, 2013). "CAIX is a tumor antigen and it is an acknowledged HIF1α target, also in MCF7-MS, where it is up-regulated by HIF1α over-expression (+93%, p<0.01) and down-regulated by HIF1α KD (−46%, p<0.01)." (PMID 23372804, 2013). "In summary, our data reveal that radiosensitization of tumor cells by Hsp90 inhibitors is independent of basal and Hsp90 inhibitor-induced HIF-1α levels." (PMID 22347438, 2012). "In hypoxic models in vitro and in in vivo models of systemic hypoxia and xenograft tumor growth, knockdown of SIRT1 protein with shRNA or inhibition of its activity with small molecule inhibitors impaired the accumulation of HIF-1α protein and the transcriptional increase of its target genes." (PMID 22479397, 2012). "We revealed that the decrease of glucose-availability results in the suppression of HIF-1α expression in pimonidazole-positive/HIF-1α-negative regions in a tumor cord (See Section 2.1)." (PMID 23203043, 2012). "The slight decrease in HIF1α expression suggests that the decreased Glut-1 expression is not due to changes in oxygen levels or tumor hypoxia." (PMID 22761648, 2012). "Notwithstanding the issue of hypoxia and radio-resistance, the potential phenotypic aggressiveness of HIF1α-negative tumor cells has been documented in series." (PMID 22546016, 2012). "Next, we performed immunohistochemistry to detect HIF-1α, CDCP1 and VHL protein in tumor tissue." (PMID 22390300, 2012). "On the other hand, experiment displayed HIF-1α could up-regulate the VEGF and GLUT1 to make tumor cell resist to apoptosis, inhibition of HIF-1α could promote apoptosis." (PMID 22453051, 2012).
tumor (continued). "They found that low HIF-1α expression indicated a poor disease-free and overall survival, while it showed no obvious effect to the tumor size, tumor differentiation, and lymph node status." (PMID 23762617, 2012). "Recent studies have focused on molecular markers of hypoxia (HIF-1α or CAIX) that demonstrate the presence of hypoxic areas within the tumours and not within healthy tissues but these surrogate markers do not give absolute values." (PMID 23139748, 2012). "The HIF1α-positive/pimonidazole-negative layer is located closer to tumor blood vessels than the pimonidazole-positive/HIF-1α-negative layer." (PMID 23203043, 2012). "2ME2 in moderate concentrations has no direct toxic effects on slowly dividing non-tumor cells, but it does lead to reliable inhibition of HIF-1α." (PMID 23133644, 2012). "In contrast to HIF-1α, HIF-2α was up-regulated upon hypoxic exposure in both tumor cell lines." (PMID 22347438, 2012). "On the one hand, HIF-1α can exert pro-survival functions, e.g., by the inhibition of apoptosis, on the other hand, HIF-1α can increase apoptosis, enhance glycolysis and induce mitosis in tumor cells, all factors leading to increased radiosensitivity." (PMID 22347438, 2012). "1400W strongly suppressed hypoxia-induced tumor cell migration through WT endothelial cells; however, it had no suppressive effect on HIF-1α and VEGF null endothelial cells." (PMID 22264788, 2012). "Some studies elucidated that HIF-2α was only significantly present in the cancer stem cells, whereas HIF-1α was present in both stem and nonstem tumour cells." (PMID 22852079, 2012). "The strong correlation with poor vascularization and the hypoxia-inducible factor-1α (HIF-1α), a marker of hypoxic tumors, indicates that NHERF1 expression might play an important role in driving metastatic progression by modifying the tumor microenvironment." (PMID 22439624, 2012). "Locating additional targets on the tumor endothelium such as nonreceptor kinases, and targeting proangiogenic pathways and agents such as HIF1-α are currently being focused to evade the resistance." (PMID 21961001, 2012). "HIF-1α induces the transcription of genes like PECAM, VE-Cadherin, VEGF and other proteins that stimulate the formation of blood vessels supplying nutrients to the tumour cells." (PMID 23185562, 2012). "Therefore, HIF-1α and HIF-1α target genes represent potential therapeutic targets to influence the effect of hypoxia on tumor radiosensitivity." (PMID 22458929, 2012). "Chemical activation of HIF-1α by using prolyl hydroxylase inhibitor was sufficient to induce angiogenic responses in a set of cell lines, including HT1080, under normoxia, clearly supporting its role in the tumour angiogenesis." (PMID 23185562, 2012). "In addition, western blot analysis showed that treatment of these agents decreased the expression of HIF1α and VEGF, both of which play an essential role in tumor angiogenesis and progression, in vitro and in vivo." (PMID 22580933, 2012). "The tumour cells were positive for CK, S-100 protein, Glut-1, HIF-1α, PI3K and p-Akt, but negative for all other markers examined." (PMID 22551172, 2012).
tumor (continued). "The pathological characteristics of serum HIF-1α were associated with the levels of circulating VEGF and Ang-2, the size of the tumor, and extrahepatic metastasis, and but not with patients’ gender, age, and AFP level." (PMID 22224081, 2011). "Through preclinical studies using a pharmacological HIF-1 inhibitor, YC-1, a dominant negative mutant of HIF-1α, or short hairpin/short interfering RNA against HIF-1α, it has been extensively confirmed that inhibition of intratumoral HIF-1 activity delayed tumor growth after radiation therapy." (PMID 24212970, 2011). "In the B16.F10 tumor model in immune-competent mice employed here, vascular morphology did however not relate to HIF-1α and VEGF mRNA levels." (PMID 22235379, 2011). "We hypothesised that tumours with high baseline levels of the PHDs and/or that are able to induce PHD after chemotherapy could modulate HIF-1α levels and thereby alter HIF signalling." (PMID 21291529, 2011). "Therefore as the abundance of molecular oxygen for hydroxylation decreases, which occurs in the hypoxic microenvironment of a tumour with its disordered and leaky vasculature, a reduction in PHD enzymatic activity occurs, allowing HIF-1α accumulation." (PMID 21291529, 2011). "This raises the interesting possibility that in cells that lack VHL and express HIF-1α, FIH-1 may favour tumour growth by decreasing the anti-proliferative consequences of HIF-1α activation and shifting the balance of HIF activation towards HIF-2α." (PMID 21386837, 2011). "Given the crucial role of HIF-1α and VEGF in regulating tumor angiogenesis, we hypothesized that miR-21 can induce angiogenesis." (PMID 21544242, 2011). "These were chosen because MEFs, unlike tumor derived or transformed cells, do not express basal levels of Hif1α which can impact intrinsic radiosensitivity." (PMID 22016813, 2011). "These pathways include VEGF-induced phosphorylation of extracellular signal-regulated kinase 1/2 (ERK1/2), serine/threonine protein kinase family protein kinase B (Akt), two tumor promoters CXC chemokine Receptor (CXCR4) and Hypoxia inducible factor 1alpha (HIF1α)." (PMID 22072999, 2011). "As the hypoxia signature was more frequent in GMP-positive tumours, GMP formation might be stimulated by hypoxia-related pathways, like HIF-1α activation and increased VEGF expression." (PMID 21673677, 2011). "Since p70S6K is a regulator for HIF-1α expression in endothelial cells, and is required for the cancer cell-induced tumor growth and angiogenesis and for vascular endothelial growth factor (VEGF) expression, we also examined HIF-1α expression in this model to observe the effect of p70S6K inhibition." (PMID 22073238, 2011). "Expression of Akt in a dominant/negative mutant also inhibited angiogenesis and tumor growth, and also decreased the expression of HIF-1α and vascular endothelial growth factor (VEGF) in tumor xenographs." (PMID 21639868, 2011). "Immunohistochemistry of these tumours demonstrated Avastin-induced necrosis, expression of HIF1α and the HIF target genes CA9 and VEGF (data not shown)." (PMID 20436681, 2010). "This suggests that in a system where both HIF1α and HIF2α are stabilized and functional, HIF2α is critical to tumour growth and survival whereas HIF1α is not." (PMID 20104230, 2010). "In comparison, HIF1α was present in both stem and non-stem tumour cell population and was only stabilized in more severe hypoxic conditions." (PMID 20104230, 2010). "In GBM, HIF-1α recruits various pro-angiogenic bone marrow-derived CD45+ myeloid cells, and tumors lacking HIF-1α exhibit few such cells and are severely impaired in their angiogenic and tumor growth phenotypes." (PMID 20414333, 2010). "CA IX is a target gene of the hypoxia-inducible transcription factor, HIF-1α, and some, but not all, studies have shown a correlation between CA IX expression and tumor hypoxia." (PMID 20828399, 2010).
tumor (continued). "Thus, abrogation of both HIF-1α and VEGF protein levels was evidenced in tissue tumor extracts by Western immunioblotting." (PMID 21179202, 2010). "Furthermore, LAQ824 inhibited the expression of angiogenic genes including angiopoietin-2, Tie-2 and survivin in endothelial cells and down regulated the expression of HIF-1α and VEGF in tumor cells." (PMID 21151768, 2010). "A selective enhancement of pro-survival molecules (Integrin-β4, p-AKT, p-MAPK, H-RAS and HIF-1α) under MCT-1 oncogenic stress could increase cancer cell growth and angiogenecity that are substantially advantageous for tumor development." (PMID 21138557, 2010). "The increased HIF1α expression was more prominent inside HCC nodules than in surrounding matrix, the latter being characterised by a major increase in vascularisation after 20W, 25W and 30W of DEN compared to non-tumour tissue (p < 0,001)." (PMID 20727157, 2010). "Similar to observations by others, our results indicate that CAIX and HIF-1α do not always co-localize in the same tumor regions." (PMID 20445750, 2010). "The pseudohypoxic VHL-defective CCRCC cells show a bias toward HIF-2α, and overproduction of HIF2α (but not HIF1α), has been found to be sufficient to override the tumor suppressor function of VHL in xenograft studies." (PMID 20652061, 2010). "Thus, combined systemic inhibition of HIF-1α and TGF-β signaling is more beneficial than either alone due to activity on the tumor cells and the bone microenvironment." (PMID 19727403, 2009). "HIF-1α and VEGF might be used as biomarkers indicating tumor infiltration and poor prognosis in human CRC." (PMID 20003271, 2009). "HIF-1α is a negative factor for tumor therapy that has a powerful role in modulating chemotherapeutic responses." (PMID 19128456, 2009). "HIF-1α expression correlated with high tumour grade (P=0.009), negative oestrogen receptor (ER) status (P=0.001) and the absence of lymph node metastasis (P=0.028)." (PMID 19724277, 2009). "HIF-1α expression correlated with high tumour grade (P=0.009), negative oestrogen receptor-α (ER) status (P=0.001) and the absence of lymph node metastasis (P=0.028)." (PMID 19724277, 2009). "Nevertheless, despite a strong correlation with CAIX, we did not observe a correlation between basal tumours and HIF-1α or between CAIX and HIF-1α in this study." (PMID 19165203, 2009). "However, those tumours with relatively lower levels of CYGB promoter methylation (MtI⩾0.25) showed stronger correlation between expression of CYGB and HIF1A expression." (PMID 19568272, 2009). "We did not found any association among HIF-1α, CXCR7 tumour expression and the different clinicopathological factors analysed in this study (data not shown)." (PMID 19352387, 2009). "This approach provided proof of principle for the tumor autonomous effects of HIF-1α and TGF-β signaling in bone metastases, but it is not readily translatable to the clinic." (PMID 19727403, 2009). "The staining pattern therefore did not resemble a hypoxia-induced HIF-1α expression, but rather the HIF-1α stabilisation was observed to result from oncogene gain of function and tumour suppressor gene loss of function, respectively." (PMID 19223895, 2009). "In rat HCC models, tumor progression after hypoxia and chemotherapy was related to up-regulation of HIF-1α and subsequent VEGF production, and transcriptional blockade of HIF-1α could enhance their therapeutic efficacy." (PMID 19948069, 2009). "One potential mechanism of retaining elevated HIF-1α in both BRCA1 and basal-like may be the relative paucity of PHD3, which showed significantly lower expression in BRCA1 tumours." (PMID 19724277, 2009). "In univariate analysis, neither the patterns of HIF-1α expression nor VEGF expression was associated with following clinical parameters: age, sex, tumor size, degree of histological differentiation, and depth of infiltration (P > 0.05)." (PMID 20003271, 2009).